DMD (dystrophin)
Description:
Anchors the extracellular matrix to the cytoskeleton via F-actin. Ligand for dystroglycan. Component of the dystrophin-associated glycoprotein complex which accumulates at the neuromuscular junction (NMJ) and at a variety of synapses in the peripheral and central nervous systems and has a structural function in stabilizing the sarcolemma. Also implicated in signaling events and synaptic transmission.
Synonyms: BMD; DXS142; DXS164; DXS206; DXS230; DXS239; DXS268; DXS269; DXS270; DXS272; CMD3B; MRX85
Tractability: Antibody: its Gene Ontology location is reachable by antibodies, with high confidence; UniProt places it where antibodies can reach, with medium confidence. PROTAC: ubiquitination databases record sites on it; its protein half-life has been measured.
Target class: Structural protein
Gene: Protein-coding gene on chromosome X (31,097,677 to 33,339,609, reverse strand). Ensembl gene ENSG00000198947.
Subcellular location: Cell membrane, sarcolemma; Cytoplasm, cytoskeleton; Postsynaptic cell membrane
Pathways (Reactome):
Extracellular matrix organization: Formation of the dystrophin-glycoprotein complex (DGC); Non-integrin membrane-ECM interactions
Muscle contraction: Striated Muscle Contraction
Gene Ontology:
Molecular function: actin binding; dystroglycan binding; myosin binding; protein binding; structural constituent of muscle; vinculin binding; nitric-oxide synthase binding; structural constituent of cytoskeleton; integrin binding; lamin binding; PDZ domain binding; protein-containing complex binding; zinc ion binding
Biological process: cardiac muscle contraction; intracellular protein localization; peptide biosynthetic process; regulation of heart rate; cardiac muscle cell action potential; maintenance of blood-brain barrier; muscle cell cellular homeostasis; muscle cell development; muscle organ development; neuron development; protein-containing complex assembly; regulation of calcium ion transmembrane transport; regulation of cardiac muscle contraction by regulation of the release of sequestered calcium ion; regulation of muscle system process; regulation of release of sequestered calcium ion into cytosol by sarcoplasmic reticulum; regulation of skeletal muscle contraction; regulation of skeletal muscle contraction by regulation of release of sequestered calcium ion; regulation of sodium ion transmembrane transport; response to muscle stretch; skeletal muscle tissue development; synaptic signaling; cell differentiation; cerebral cortex development; cytoskeleton organization; muscle cell differentiation; and 12 more
Cellular component: cell surface; costamere; dystrophin-associated glycoprotein complex; filopodium; filopodium membrane; protein-containing complex; sarcolemma; cell-substrate junction; cytoskeleton; cytosol; lateral plasma membrane; membrane raft; neuron projection terminus; postsynaptic membrane; synapse; syntrophin complex; Z disc; astrocyte projection; axon; cell junction; GABA-ergic synapse; lamellipodium; matrix side of mitochondrial inner membrane; mitochondrial outer membrane; myofibril; and 11 more
Gene-disease validity (ClinGen):
ClinGen rates the evidence that DMD causes each of these diseases.
progressive muscular dystrophy (X-linked): Definitive.
Homologues: Orthologues: chimpanzee DMD (99% identical), macaque DMD (98% identical), guinea pig DMD (92% identical), rat Dmd (92% identical), mouse Dmd (91% identical), tropical clawed frog DMD (72% identical), pig DMD (60% identical), zebrafish dmd (14% identical). Paralogues in human: UTRN (46% identical), MACF1 (16% identical), DST (16% identical), PLEC (14% identical), SYNE1 (14% identical), DRP2 (14% identical), SYNE2 (13% identical), SPTB (11% identical), SPTBN1 (11% identical), SPTBN2 (11% identical), SPTBN4 (11% identical), SPTBN5 (10% identical), and 24 more.
Diseases named in the same sentence as DMD in open-access papers:
DMD is named in the same sentence as 375 diseases in open-access papers, as found by Europe PMC text mining. Sharing a sentence is not in itself a finding about the gene and the disease. The quoted sentences say what the papers report.
Duchenne muscular dystrophy (1,917 papers, 2005 to 2026). Duchenne muscular dystrophy (DMD) is a neuromuscular disease characterized by rapidly progressive muscle weakness and wasting due to degeneration of skeletal, smooth and cardiac muscle. "Duchenne muscular dystrophy (DMD) is a progressive, severe muscle-wasting disease caused by mutations in DMD, encoding dystrophin, that leads to loss of muscle function with cardiac/respiratory failure and premature death." (PMID 42236981, 2026). "Both of these strains lack the full length skeletal muscle dystrophin isoform, which when it occurs in humans is the cause of Duchenne muscular dystrophy." (PMID 40542412, 2025). "In the present study, the cause of Duchenne muscular dystrophy in three girls was reciprocal translocations t(X;2), t(X;12), and t(X;16), with breakpoints located within the DMD gene sequence." (PMID 41096657, 2025). "Duchenne muscular dystrophy (DMD) is an X‐linked recessive neuromuscular disease caused by mutations of genes that encode dystrophin protein." (PMID 40034097, 2025). "An increased number of Pax7-positive cells has also been observed in the muscle of patients with Duchenne muscular dystrophy and dystrophin-deficient mdx mice." (PMID 41397955, 2025). "Dystrophin is an intracellular protein that is encoded by the duchenne muscular dystrophy (DMD) gene." (PMID 39773412, 2025). "Duchenne muscular dystrophy (DMD) is a severe X-linked disorder caused by mutations in the DMD gene, and it has a global prevalence of 3.6 per 100,000 people." (PMID 41179496, 2025). "Duchenne muscular dystrophy (DMD) is a fatal X-chromosome-linked genetic disease caused by dystrophin gene mutations, including nonsense mutations." (PMID 40491751, 2025). "Duchenne muscular dystrophy (DMD) is an X-linked recessive disorder caused by mutations in the DMD gene encoding dystrophin, a protein that protects muscle from damage during contraction." (PMID 40579547, 2025). "Duchenne muscular dystrophy (DMD) is the most common inherited muscle-wasting disease in boys and is caused by null mutations in the DMD gene." (PMID 40557917, 2025). "Duchenne muscular dystrophy (DMD) is a recessive X‐linked disorder caused by pathogenic variants in the DMD gene, which encodes the dystrophin protein." (PMID 40329488, 2025). "Eccentric contraction–induced (ECC-induced) force loss is a hallmark of murine dystrophin-deficient (mdx) skeletal muscle that is used to assess efficacy of potential therapies for Duchenne muscular dystrophy." (PMID 39808494, 2025). "Investigating the relationship between the location of mutations in the DMD gene and cognitive deficits in children with Duchenne muscular dystrophy." (PMID 40291285, 2025). "Duchenne muscular dystrophy (DMD) is a rare, progressive genetic disorder primarily affecting males, caused by mutations in the DMD gene that lead to dystrophin deficiency." (PMID 39861752, 2025). "Duchenne muscular dystrophy (DMD) is an X-linked hereditary neuromuscular disorder caused by mutations in the DMD gene encoding dystrophin protein." (PMID 40970088, 2025). "Duchenne muscular dystrophy (DMD) is a fatal neuromuscular disease caused by loss‐of‐function mutations in the X‐linked dystrophin gene (DMD)." (PMID 39723578, 2025). "Duchenne muscular dystrophy (DMD) is a severe genetic muscle disease occurring due to mutations of the dystrophin gene and loss of dystrophin expression." (PMID 39851544, 2025). "Duchenne muscular dystrophy (DMD) results from mutations in DMD, that leads to severe, progressive global muscle-wasting due to the loss of functional dystrophin expression." (PMID 40268053, 2025). "A suggestive significant association was observed for two markers associated with the DMD gene, which is linked to Duchenne muscular dystrophy." (PMID 40831500, 2025).
Duchenne muscular dystrophy (continued). "Duchenne muscular dystrophy (DMD) is an X-linked neuromuscular disease with an incidence in 1 in 3500 to 5000 newborn boys caused by mutations in the Dystrophin (DMD) gene, the largest gene known to humans." (PMID 41227334, 2025). "While altered dystrophin expression leads to the developmental onset of Duchenne muscular dystrophy, it also has been associated with downregulation across various malignancies and enrichment across multiple pathways within transcriptomes of primary tumors." (PMID 41590495, 2025). "Duchenne muscular dystrophy (DMD) is a severe X-linked recessive disorder caused by mutations in the DMD gene, leading to progressive muscle degeneration and fibrosis." (PMID 41009414, 2025). "Duchenne muscular dystrophy (DMD) is a severe genetic muscle disease occurring due to mutations of the dystrophin gene." (PMID 39851544, 2025). "Duchenne muscular dystrophy (DMD) is the most common X-linked recessive disorder caused by mutations in the DMD gene, which encodes the protein dystrophin." (PMID 41009414, 2025). "Becker muscular dystrophy (BMD) is due to Duchenne muscular dystrophy gene variants allowing partial expression of dystrophin." (PMID 40735474, 2025). "We also identified mis-splicing in the DMD gene, known to underlie Duchenne muscular dystrophy associated with ASD42,43." (PMID 40259070, 2025). "In BMD muscle tissues, truncated and reduced dystrophin is expressed; therefore, its clinical status is generally milder than that of Duchenne muscular dystrophy (DMD), an allelic disorder with complete loss of dystrophin." (PMID 40094282, 2025). "Duchenne muscular dystrophy (DMD) is a severe, X-linked genetic disorder caused by mutations in the DMD gene, which encodes dystrophin, an essential structural muscle protein." (PMID 41328300, 2025). "Duchenne muscular dystrophy (DMD) is a lethal disease caused by mutations in the DMD gene that encodes dystrophin." (PMID 39477543, 2025). "Duchenne muscular dystrophy is a severe neuromuscular disorder, caused by mutations in the DMD gene." (PMID 39885828, 2025). "Duchenne muscular dystrophy (DMD) is an X-chromosome-linked disease caused by loss-of-function mutations in the human dystrophin gene, leading to severe and progressive muscle wasting." (PMID 40332229, 2025). "Over 30 muscular dystrophies have been classified, with the most well studied being Duchenne muscular dystrophy (DMD) caused by mutations in the dystrophin gene." (PMID 40549548, 2025). "Duchenne Muscular Dystrophy (DMD) is a rare X-linked genetic disorder caused by a mutation in the dystrophin gene that leads to severe progressive muscle weakness and premature death." (PMID 40103935, 2025). "Duchenne Muscular Dystrophy (DMD) occurs due to defects in the gene encoding for dystrophin and is the most common muscular dystrophy in children, with an incidence of about 1 in 5000 live males every year." (PMID 40422224, 2025). "Duchenne Muscular Dystrophy (DMD) is a severe X-linked recessive disorder characterized by progressive muscle degeneration due to dystrophin deficiency." (PMID 40004149, 2025). "The most common genetic mutation is Duchenne Muscular Dystrophy (DMD), caused by an x-linked mutation of the DMD gene and thereby predisposing males." (PMID 40166018, 2025). "Duchenne muscular dystrophy is a fatal muscular disease caused by mutations in the DMD gene, in turn causing severe symptoms such as muscle weakness and wasting, ultimately leading to a shortened life span in affected individuals." (PMID 41227334, 2025). "Duchenne muscular dystrophy is a severe X-linked recessive genetic disorder caused by mutations in the dystrophin gene, leading to the absence or dysfunction of the dystrophin protein." (PMID 41322400, 2025). "Duchenne muscular dystrophy (DMD) is a progressive, disabling, and life-limiting disease caused by mutations in the DMD gene on the X chromosome, in 15.9 to 19.5 live male births per 100,000." (PMID 40577272, 2025).
Duchenne muscular dystrophy (continued). "Duchenne muscular dystrophy (DMD) results from numerous mutations in the DMD gene, the largest known gene, spanning about 2.4 million base pairs of genomic DNA." (PMID 41328300, 2025). "Duchenne muscular dystrophy (DMD) is a severe neuromuscular disease caused by mutations in the DMD gene, leading to muscle degeneration and shortened life expectancy." (PMID 41002406, 2025). "D﻿uch﻿enne muscular dystrophy is a severe, X-linked inherited disorder caused by loss of the dystrophin protein affecting 1:3500–5000 boys worldwide." (PMID 39883376, 2025). "Duchenne muscular dystrophy (DMD) is an X-linked hereditary disease characterized by a structural defect in dystrophin, affecting muscle cells, leading to their progressive degeneration." (PMID 40303537, 2025). "Duchenne muscular dystrophy (DMD) is a lethal inherited muscle disease caused by mutations in the DMD gene, and the development of gene therapies targeting DMD is rapidly progressing." (PMID 40940738, 2025). "For example, Ataluren, a small-molecule compound, is now approved by the European Medicine Agency to treat male patients with Duchenne muscular dystrophy, a disease caused by non-sense mutations in the dystrophin gene." (PMID 40709001, 2025). "Duchenne muscular dystrophy is an X-linked genetic disorder caused by the absence of dystrophin expression, a gene that encodes a 427-kDa protein that connects the cytoskeleton to the sarcolemma and the extracellular matrix." (PMID 40331939, 2025). "Duchenne muscular dystrophy (DMD), which impacts one in every 5000 male births worldwide, is caused by mutations in the X-linked DMD gene, which lead to the loss of expression of the protein product dystrophin." (PMID 40473604, 2025). "Genetic defects in dystrophin cause Duchenne muscular dystrophy (DMD) that manifests as severe neuromuscular defects and cardiac arrhythmias." (PMID 39626239, 2025). "In patients with Duchenne muscular dystrophy, a significant reduction in dystrophin is observed, an aspect associated with mutations in the DMD gene linked to the X chromosome." (PMID 39846639, 2025). "One of the best-characterized models is Drosophila Duchenne muscular dystrophy (DMD), caused by mutations in the Dys gene, the fly homolog of the human DMD gene." (PMID 39722550, 2025). "Duchenne muscular dystrophy is caused by pathogenic variants (deletions, duplications, point variants, and other more rare variants) in the dystrophin (abbreviated DMD) gene that result in the loss of dystrophin protein." (PMID 40695995, 2025). "Shortly after the discovery that mutations in the DMD (dystrophin) gene caused Duchenne muscular dystrophy, an international consortium was established to find the ‘FSHD’ gene." (PMID 40855454, 2025). "Duchenne muscular dystrophy is a genetic disease where loss of sarcolemma-associated protein, dystrophin, leads to progressive muscle wasting, and eventual loss of life from complications linked to cardiac deficits." (PMID 40970088, 2025). "Dystrophin-deficient zebrafish larvae are a small, genetically tractable vertebrate model of Duchenne muscular dystrophy that is well suited for early-stage therapeutic development." (PMID 40542412, 2025). "Duchenne muscular dystrophy (DMD) is a fatal X‐linked recessive disease due to loss‐of‐function variants in the DYSTROPHIN gene." (PMID 40641092, 2025). "Approximately two-thirds of the patients who carried DMD gene missense variants or deletions had Duchenne muscular dystrophies (DMD), one-third had Becker muscular dystrophies (BMDs), and two were female symptomatic carriers." (PMID 40883749, 2025). "In our analysis, viltolarsen (indication for Duchenne muscular dystrophy with deletion of the dystrophin-encoding gene that can be treated by exon 53 skipping, approved on March 25, 2002) is the only product for which this system was applied." (PMID 40223100, 2025).
Duchenne muscular dystrophy (continued). "Current gene therapy for Duchenne muscular dystrophy utilizes adeno-associated virus to deliver a partially functional copy of truncated dystrophin." (PMID 39034316, 2024). "Malfunctioning dystrophin is a primary cause of Duchenne muscular dystrophy (DMD), characterized by ischemic damage and myocyte cell death, resulting in the replacement of functional muscle tissues with fibrotic and non-functional adipose tissue." (PMID 39555101, 2024). "In the United States, delandistrogene moxeparvovec has received approval for the treatment of ambulatory children aged 4 to 5 years with Duchenne muscular dystrophy (DMD) who have a verified mutation in the DMD gene." (PMID 39684857, 2024). "As an example, the dystrophin-deficient mdx mouse model of Duchenne muscular dystrophy shows high Orai1 expression levels associated with increased SOCE activity." (PMID 38516893, 2024). "Duchenne muscular dystrophy (DMD) is caused by a faulty dystrophin protein, which is approximately in 19.8 out of 100,000 male births worldwide and is wrongly encoded by the DMD gene on chromosome X." (PMID 40729158, 2024). "For example, the mdx mouse carries a point mutation in the dystrophin genes, the same gene that is disrupted in Duchenne muscular dystrophy (DMD) patients." (PMID 38812056, 2024). "Duchenne muscular dystrophy (DMD) is a fatal muscle wasting disease caused by mutations in the dystrophin gene resulting in cycles of muscle degeneration, inflammation and regeneration." (PMID 40292009, 2024). "Duchenne muscular dystrophy (DMD) is caused by genetic mutations in the cytoskeletal-sarcolemmal anchor protein dystrophin." (PMID 39061981, 2024). "The most abundant variant in this list, the R2095X mutation (UGA) in the Duchenne muscular dystrophy DMD gene demonstrated readthrough in response to +8 R-ASO combined with G418 or Ser-tRNAUGA." (PMID 39011883, 2024). "Duchenne muscular dystrophy (DMD) is an X-linked disorder caused by mutations in the dystrophin gene." (PMID 38564291, 2024). "Duchenne muscular dystrophy (DMD) is a severe form of muscular dystrophy caused by X chromosome-linked mutations in the dystrophin gene." (PMID 38543122, 2024). "Duchenne muscular dystrophy (DMD) is an X-linked recessive disorder that affects 1 in 5000 boys globally and is caused by mutations in the dystrophin (DMD) gene." (PMID 38721692, 2024). "Two drugs gained approval for the treatment of Duchenne muscular dystrophy (DMD), a rare X-linked genetic neuromuscular disorder resulting from mutations in the DMD gene, which encodes dystrophin, a protein crucial for proper muscle function." (PMID 38530400, 2024). "Duchenne muscular dystrophy (DMD) is an X-linked recessive myopathy resulting from mutations in the gene encoding the membrane-associated protein dystrophin." (PMID 38790635, 2024). "Duchenne Muscular Dystrophy (DMD) is a fatal disorder caused by mutations in the dystrophin gene characterized by progressive muscular weakening." (PMID 38628493, 2024). "Female carriers of Duchenne Muscular Dystrophy (DMD) carry a heterozygous pathogenic variant in the dystrophin gene and can transmit pathogenic variants to their offspring." (PMID 39075955, 2024). "Duchenne muscular dystrophy (DMD) originates from a mutation in the dystrophin gene that results in more progressive muscle weakness and severe cardiomyopathy." (PMID 38725755, 2024). "Genomic alterations in the DMD gene are clinically implicated in Duchenne muscular dystrophy, an X-linked neuromuscular disorder in a group of hereditary muscular dystrophies resulting from a failure in the protein translation of dystrophin." (PMID 39338204, 2024). "Duchenne muscular dystrophy (DMD) is a fatal muscle disorder caused by the lack of the dystrophin protein, which is characterized by cycles of degeneration and regeneration leading to irreversible muscle degeneration and fibrosis." (PMID 38338718, 2024).